AGT (angiotensinogen)
Diseases named in the same sentence as AGT in open-access papers (continued):
Sharing a sentence is not in itself a finding about the gene and the disease.
systemic lupus erythematosus (9 papers, 2012 to 2025). An autoimmune multi-organ disease typically associated with vasculopathy and autoantibody production. "Genes, like angiotensin-converting enzyme (ACE) or angiotensinogen (AGT), that specifically increase kidney susceptibility to lupus pathogenesis have also been described." (PMID 22761632, 2012). "In addition, several autoimmunity-related proteins are linked to coagulation (e.g., AGT, F2) and to specific ADs, such as systemic lupus erythematosus (e.g., AGT, C1S, C7, MMP2, VWF) or autoimmune rheumatic diseases (e.g., ADIPOQ, AGT, MASP1, MMP2)." (PMID 40546301, 2025).
vasculitis (9 papers, 2020 to 2026). "Among the KD-related proteins, LRG1 and AGT are associated with vasculitis and CALs in KD patients." (PMID 34499692, 2021).
lung adenocarcinoma (8 papers, 2018 to 2024). A carcinoma that arises from the lung and is characterized by the presence of malignant glandular epithelial cells. "They found that a fraction of the angiotensinogen produced by tumors may be locally converted into Ang II in a mouse model of lung adenocarcinoma." (PMID 37415162, 2023). "However, an article pointed out AGT was overexpressed in lung adenocarcinoma tissue." (PMID 32090070, 2020). "TCGA and GTEx database results showed significant differences in the expression of enzymes and transporters related to oxalate metabolism (LDHA, GRHPR, AGT, DAO, HAO2 and SLC26A1) in tumor tissues of lung adenocarcinoma patients." (PMID 38567154, 2024). "Finally, we show that AGT and HMGA1 mRNAs were upregulated while KLF6 mRNA was downregulated in human lung adenocarcinoma, as demonstrated by The Cancer Genome Atlas analysis." (PMID 33380422, 2021).
melanoma (8 papers, 2010 to 2023). A malignant, usually aggressive tumor composed of atypical, neoplastic melanocytes. "Additionally, angiotensinogen, as well as des-Angiotensin I angiotensinogen, has antiangiogenic effects and reduces metastasis of B16-F10 melanoma cells to the lungs of mice." (PMID 28791183, 2017).
polycystic kidney disease (8 papers, 2012 to 2025). A usually autosomal dominant and less frequently autosomal recessive genetic disorder characterized by the presence of numerous cysts in the kidneys leading to end-stage renal failure. "AGT and ACE variants were associated with renal tubular dysgenesis, while PKD1 and PKHD1 mutations indicated both dominant and recessive polycystic kidney disease." (PMID 41288877, 2025). "In order to investigate the origin of AGT expression in polycystic kidneys, immunohistochemistry was performed using normal and polycystic kidney tissues." (PMID 26092580, 2015). "In addition, our immunohistochemical staining results showed that most of RAS components including AGT were highly expressed in the polycystic kidney tissues compared to normal kidney." (PMID 26092580, 2015). "Interestingly, we found that a number of the nodes had previously been linked to polycystic kidney disease (TNF, AGT, AVP)." (PMID 23209428, 2012). "AGT ASO decreased kidney size, cyst volume density, and blood urea levels in mouse models for polycystic kidney disease, and this was accompanied by a reduction in fibrosis and inflammation." (PMID 35904033, 2022).
arteriosclerosis (7 papers, 2013 to 2025). A vascular disorder characterized by thickening and hardening of the walls of the arteries. "Meanwhile, bioactive substances secreted by adipose tissue, such as angiotensinogen, IL-6 and TNF-α, are associated with changes in vascular inflammation and arteriosclerosis, leading to increased blood pressure." (PMID 35937205, 2022).
cyst (7 papers, 2012 to 2023). A sac-like closed membranous structure that may be empty or contain fluid or amorphous material. "This theory has been supported by a report of amelioration of cyst growth by suppression of AGT synthesis in PKD1 animal model." (PMID 38027263, 2023). "In concordance to previous study results, AGT was highly expressed in proximal tubular epithelial cells and cyst-lining cells of ADPKD." (PMID 26092580, 2015). "Immunohistochemical study showed strong expression of AGT along the cyst-lining epithelial cells as well as the nearby compressed tubular epithelial cells." (PMID 26092580, 2015). "On the other hand, in case I (PKD-CKD), AGT was strongly expressed in proximal tubules and cyst-lining epithelial cells." (PMID 26092580, 2015). "The renin-angiotensin system (AGT) has been reported to accelerate disease progression by enhancing fibrosis and promoting cyst growth." (PMID 23209428, 2012). "Indeed, AGT is highly expressed in cyst lining cells of ADPKD patients." (PMID 38027263, 2023). "Presence of RAAS components (AGT, ACE, ANG II and angiotensin II type I receptor) within cysts and tubules and activation of RAAS during cyst expansion in ADPKD has also been demonstrated." (PMID 28197498, 2016).
nephrosclerosis (7 papers, 2014 to 2024). Hardening of the kidney due to infiltration by fibrous connective tissue (fibrosis), usually caused by renovascular diseases or chronic hypertension. "Klotho supplementation reduces BP, renal angiotensinogen, Ang II, and HIF-1, mammalian target of rapamycin (mTOR), Akt, and medullary fibrosis in adult SHR-SP with nephrosclerosis." (PMID 39765782, 2024).
pancreatitis (7 papers, 2014 to 2025). Inflammation of the pancreas. "Major components of the renin-angiotensin-aldosterone system (angiotensinogen and angiotensin receptors 1 and 2) were upregulated in rat pancreatic acinar cells during pancreatitis and treatment with the angiotensin receptor antagonist losartan inhibited the acinar digestion enzyme secretion." (PMID 38510657, 2024). "All these data indirectly hinted that their upstream regulator, tRF3-Thr-AGT, might support its involvement in pancreatitis." (PMID 35045793, 2022).
resistant hypertension (7 papers, 2013 to 2025). "One of the genes most commonly associated with resistant hypertension is the angiotensinogen (AGT) gene." (PMID 37416924, 2023). "Another study has reported that the angiotensinogen AGT 235 T allele constitutes an independent risk factor for resistant hypertension." (PMID 25492217, 2014). "In addition the Angiotensinogen AGT 235 T allele has also been shown to be an independent risk factor for resistant hypertension." (PMID 24053215, 2013). "In the KARDIA-1 trial, zilebesiran produced sustained 24 h SBP reductions (~15 mmHg at 6 months) with pronounced nighttime BP lowering, while IONIS-AGT-LR achieved >50% suppression of plasma AGT with favorable BP trends, particularly in resistant hypertension cohorts." (PMID 40364148, 2025).
Abdominal obesity (6 papers, 2012 to 2024). Excessive fat around the stomach and abdomen. "The renin angiotensin system is completely expressed in human adipose tissue, and the synthesis by adipocytes of angiotensinogen—precursor of the major vasoconstrictor hormone angiotensin II—is increased in central obesity." (PMID 24278711, 2012).
acute pancreatitis (6 papers, 2021 to 2023). An acute inflammatory process that leads to necrosis of the pancreatic parenchyma. "Three targeted genes, Btg2, Zbp1, and Cd44, indirectly support the association between PAITA and tRF3-Thr-AGT in the mechanisms underlying acute pancreatitis initiation." (PMID 35045793, 2022).
adenoma (6 papers, 2018 to 2025). A neoplasm arising from the epithelium. "Cortisol production from the adenoma may elevate PRA levels by increasing the renin substrate angiotensinogen while suppressing aldosterone secretion through the ACTH pathway." (PMID 35482752, 2022).
amyloidosis (6 papers, 2005 to 2025). A disorder characterized by the localized or diffuse accumulation of amyloid protein in various anatomic sites. "Misfolding of transthyretin (meningovascular amyloidosis), angiotensinogen, β2 – microglobulin, lysozyme, the Notch3 gene product, and the familial prion protein may each lead to amyloidosis." (PMID 16321154, 2005).
astrocytoma (6 papers, 2004 to 2025). "The present study aimed to determine the relationship between the AGT rs5050 germline genetic variant with prognosis in astrocytoma." (PMID 30383794, 2018). "The aim of this study was to determine the relationship between the AGT rs5050 genetic variant in blood with prognosis in astrocytoma." (PMID 30383794, 2018). "In patients with astrocytoma, AGT rs5050 GG-genotype was associated with poor prognosis." (PMID 30383794, 2018). "Among these, Sulfhydryl oxidase 1 (Qsox1), involved in tumor cell invasion and subsequent metastasis was found downregulated in cluster 1 such as CD166, TIMP2 and AGT knew to be involved in astrocytoma (cluster 1)." (PMID 33402730, 2022). "The AGT rs5050 GG carriers with astrocytoma were more likely to have poor prognosis." (PMID 36836041, 2023).
autonomic dysfunction (6 papers, 2011 to 2021). "For example, adrenal angiotensinogen was shown to be activated by adrenal renin in autonomic dysfunction." (PMID 28732007, 2017).
breast tumor (6 papers, 2006 to 2023). "AGT mRNA was detected at relatively low, although significant levels in both normal breast and in breast tumour samples." (PMID 16755291, 2006). "Most components of the RAS including angiotensinogen, angiotensin converting enzyme (ACE) and angiotensin receptors are expressed locally in a wide variety of tumors, including in breast tumors." (PMID 22536420, 2012).
hyperthyroidism (6 papers, 2010 to 2021). Overactivity of the thyroid gland resulting in overproduction of thyroid hormone and increased metabolic rate. "Another possibility for the increment of serum sodium value might be of the direct relation of hyperthyroidism with plasma rennin activity, and plasma level of angiotensinogen, angitension II and aldosterone." (PMID 28154693, 2016).
ischemic cardiomyopathy (6 papers, 2022 to 2025). Ischemic cardiomyopathy is a cardiomyopathy in which a weakness in the muscle of the heart due to inadequate oxygen delivery to the myocardium with coronary artery disease being the most common cause. "Among them, C3 AGT + Fibroblasts had the highest percentage of ischemic cardiomyopathy (RM), and coincidentally ICM had a worse prognosis." (PMID 38799173, 2024).
liver cancer (6 papers, 2021 to 2026). An epithelial or non-epithelial malignant neoplasm that arises from the liver. "Consistent with its expression in tissues, AGT was maximally expressed in liver cancer and relatively highly expressed in bile duct carcinoma, kidney cancer and brain cancer, partially corresponding to the results in LGG and GBM tissues." (PMID 34671200, 2021).
lung disease (6 papers, 2012 to 2023). "It is hoped that the further analysis of additional SNPs in the AGT gene will reveal an “IPF risk haplotype” in AGT that might hold significant predictive value in the treatment of IPF and possibly other lung diseases that are influenced by lung AGT expression." (PMID 22500179, 2012).
nephrotic syndrome (6 papers, 2016 to 2025). A collection of symptoms that include severe edema, proteinuria, and hypoalbuminemia; it is indicative of renal dysfunction. "The renal Ang II generation from the leaked plasma AGT may be a mechanism underlying the overfill hypothesis of nephrotic syndrome (i.e., proteinuria primarily stimulates sodium reabsorption)." (PMID 35710133, 2022). "Future studies should also investigate how hepatic AGT ensures local generation of Ang II at the level of the CD, which is an important site for controlling sodium reabsorption in nephrotic syndrome." (PMID 35710133, 2022).
vascular dementia (6 papers, 2019 to 2025). A degenerative vascular disorder affecting the brain. "Thus, the inhibition of angiotensinogen might be a promising therapeutic option for subcortical vascular dementia." (PMID 35455468, 2022).
angina (5 papers, 2018 to 2024). "Analysis of cardiac ventricle samples taken during biopsies from patients with stable and unstable angina revealed that the patients with unstable angina synthesize more Ang II and have higher expressions of angiotensinogen, angiotensin converting enzyme (ACE) and AT1R genes." (PMID 36430892, 2022).
epilepsy (5 papers, 2019 to 2025). A brain disorder characterized by episodes of abnormally increased neuronal discharge resulting in transient episodes of sensory or motor neurological dysfunction, or psychic dysfunction. "Our study demonstrated AGT overexpression in the epilepsy group compared to the healthy group." (PMID 39063177, 2024).
gestational diabetes (5 papers, 2014 to 2025). Carbohydrate intolerance first diagnosed during pregnancy. "Multiple logistic regression analysis adjusting for maternal age, fetal sex, and gestational diabetes mellitus showed significant associations between angiotensinogen (AGT) rs3789678 T/C and GH (p = 0.0088) and between angiotensin II receptor type 1 (AGTR1) rs275645 G/A and PE (p = 0.0082)." (PMID 27910864, 2016). "As a result, the current study may be the first to report significantly elevated urine angiotensinogen/creatinine levels in gestational diabetes." (PMID 35309508, 2022).
hypothyroidism (5 papers, 2019 to 2025). Abnormally low levels of thyroid hormone. "Fetal hypothyroidism was found to have temporal and tissue‐specific effects on the expression of many RAS genes including AGT, ACE, ACE2, AGTR1, and AGTR2." (PMID 40939099, 2025). "However, the implication of angiotensinogen (Agt) and vascular smooth muscle cells (VSMCs) dysfunction in the pathophysiology of cardiovascular manifestations in hypothyroidism have not yet been investigated." (PMID 37951959, 2023).
peripheral artery disease (5 papers, 2018 to 2023). "In patients with peripheral arterial disease, the association between AGT rs699 CC genotype and high-density lipoprotein (HDL) levels was proved to be significant." (PMID 36836041, 2023).
endometriosis (4 papers, 2021 to 2025). The growth of functional endometrial tissue in anatomic sites outside the uterine body. "The levels of AGT were also 1.9-fold higher in the endometriosis patients versus the control patients (p = 0.0199)." (PMID 34686725, 2021). "This study also reports the first time that the proteins COMP, AGT, TGFBI and ANGP4 have been associated with endometriosis." (PMID 34686725, 2021). "However, they did not provide any evidence for association of AGT with the development or clinical course of endometriosis, and did not indicate any prognostic value for AGT43." (PMID 34686725, 2021). "According to our review of the literature here, COMP, AGT, TGFBI and ANGP4 have not yet been associated with endometriosis, while S100A8, C163A, EGFR and TIMP1 have." (PMID 34686725, 2021). "For three candidate biomarkers, COMP, TGFBI and AGT, with increased levels in the peritoneal fluid no earlier reports in the context of endometriosis were found." (PMID 34686725, 2021).
hypotension (4 papers, 2015 to 2024). "Renin released in response to increased Na+ retention and local renal hypotension converts angiotensinogen to angiotensin I (Ang I), which is further cleaved to give Ang II by the angiotensin converting enzyme (ACE)." (PMID 30314359, 2018).
magnesium deficiency (4 papers, 2020 to 2025). A nutritional condition produced by a deficiency of magnesium in the diet, characterized by anorexia, nausea, vomiting, lethargy, and weakness. "In this study, we have identified that the reduced glomerular filtration rate of angiotensinogen-deficient mice leads to iron deficiency due to hepcidin accumulation in blood." (PMID 39869503, 2025).
osteosarcoma (4 papers, 2016 to 2025). A usually aggressive malignant bone-forming mesenchymal neoplasm, predominantly affecting adolescents and young adults. "This study aimed to determine the interactions between parathyroid hormone type 1 receptor (PTHR1) and angiotensinogen (AGT) and the effects of these agents on osteosarcoma (OS)." (PMID 33511766, 2021).
renal tubular dysgenesis (4 papers, 2021 to 2025). "Variants in ACE and AGT, associated with renal tubular dysgenesis, were classified as VUS (11.8%)." (PMID 41288877, 2025). "Genetic loss of function of AGT (angiotensinogen), REN (renin), ACE (angiotensin-converting enzyme), or AGTR1 (type-1 angiotensin II receptor) leads to renal tubular dysgenesis (RTD)." (PMID 33768328, 2021).
schizophrenia (4 papers, 2015 to 2022). A major psychotic disorder characterized by abnormalities in the perception or expression of reality. "Studies on cardiovascular genomics and cognitive function in patients with schizophrenia revealed some missense mutations of angiotensinogen (AGTM268T, AGT235T)." (PMID 35207180, 2022). "Reduced angiotensinogen (AGT) in males, and increased alpha-1 acid glycoprotein (ORM1) in females were the most significant sex-specific protein features in patients with schizophrenia." (PMID 34741130, 2022). "Among these, the four genes most strongly altered in schizophrenia were WFS1 (P = 1.8×10−7), angiotensinogen (AGT, P = 1.3×10−6), LRP4 (P = 2.7×10−6), and TNS2 (P = 9.3×10−4), all of which were increased in schizophrenia." (PMID 29249829, 2017).
type 2 diabetic nephropathy (4 papers, 2009 to 2021). "Our previous studies identified NAP and six urinary markers, including three tubular markers (KIM-1, NGAL, and L-FABP), two pro-inflammatory markers (IL-18 and YKL-40), and a marker of intrarenal RAS status (angiotensinogen), as biomarkers for the early detection of type 2 diabetic nephropathy." (PMID 28912839, 2017).
acute tubular necrosis (3 papers, 2010 to 2025). "On the other hand, increased levels of angiotensinogen and Ang II have been observed in acute tubular necrosis, with the intrarenal RAS correlating with the severity of AKI." (PMID 40880342, 2025).
cervical carcinoma (3 papers, 2012 to 2023). A carcinoma arising from either the exocervical squamous epithelium or the endocervical glandular epithelium. "The AGT haplotype (which includes the rs1801270A allele) was the most frequent haplotype among all subjects, and both homozygosity and heterozygosity for the AGT haplotype provided a protective effect from development of cervical cancer." (PMID 23231583, 2012). "The AGT haplotype formed by three p21 SNPs in LD (rs1801270, rs3176352 and rs1059234) also provided a protective effect in development of cervical cancer in this population." (PMID 23231583, 2012). "We assessed the expression of WT1, AGT, MIEN1 and SPOUTY4 across cervical cancer tissues via IHC." (PMID 38028542, 2023).
cholangiocarcinoma (3 papers, 2020 to 2024). A carcinoma that arises from the intrahepatic biliary tree (intrahepatic cholangiocarcinoma) or from the junction, or adjacent to the junction, of the right and left hepatic ducts (hilar cholangiocarcinoma). "AGT showed maximal expression in multiple cancers, including liver hepatocellular carcinoma (LIHC), cholangiocarcinoma (CHOL), GBM, low-grade glioma (LGG), KIRC and KIRP." (PMID 34671200, 2021).
diabetic neuropathy (3 papers, 2015 to 2021). A chronic, pathological complication associated with diabetes mellitus, where nerve damages are incurred due to diabetic microvascular injury involving small blood vessels that supply these nerves, resulting in peripheral and/or autonomic nerve dysfunction. "With the progression of diabetic neuropathy, there is an increase in the concentrations of monocyte chemotactic protein 1 (MCP-1), angiotensinogen (AGT), and liver-type fatty acid-binding protein (L-FABP)." (PMID 34832765, 2021).
Hyperoxaluria (3 papers, 2014 to 2026). Increased excretion of oxalates in the urine. "In this study, Agxt-/- mice lacking exons 3-8 were characterized, confirming the complete loss of hepatic alanine-glyoxylate aminotransferase (AGT) expression and the presence of early-onset hyperoxaluria." (PMID 41972717, 2026).